KRAS (KRas proto-oncogene, GTPase)
Diseases named in the same sentence as KRAS in open-access papers (continued):
Sharing a sentence is not in itself a finding about the gene and the disease.
mucinous adenocarcinoma (continued). "Similarly, low body-mass index at presentation, mucinous adenocarcinoma, lymphovascular invasion, perineural invasion and KRAS mutations were independent factors significantly associated with poor disease-free survival." (PMID 35905109, 2022). "The detection of KRAS mutations supports a diagnosis of pulmonary invasive mucinous adenocarcinoma." (PMID 35545933, 2022). "The third case included a mucinous adenocarcinoma and the tubular adenoma from which the carcinoma initiated; both lesions resulted wild type for the tested genes, except for a p.G12V point mutation in the KRAS gene." (PMID 33712927, 2021). "In mucinous carcinoma, KRAS mutation (p.G12D) were detected in two cases (66.7%)." (PMID 33207545, 2020). "Interestingly, in 15% of mucinous carcinomas, multiple KRAS mutations were detected, further supporting the key role of KRAS mutations in the pathway of neoplastic transformation involving mucinous adenoma-borderline tumor-carcinoma." (PMID 29389895, 2018). "KRAS mutation was detected more frequently in mucinous adenocarcinoma." (PMID 25760072, 2015). "However, both BRAFV600E and KRAS mutated carcinomas were more likely to be located in the proximal colon and mucinous carcinomas." (PMID 25929517, 2015). "Interestingly, tumors with a KRAS mutation tended to occur more frequently in mucinous adenocarcinomas compared with the tubular subtype, which further supports previous findings." (PMID 26691448, 2015). "Clinicopathological features previously reported to be associated with CIMP positive epigenotype include female sex, older age of diagnosis, proximal colon, poor differentiation, mucinous carcinoma, low frequency of KRAS mutation, and high frequency of BRAF mutation." (PMID 24822060, 2014). "Interestingly, overexpression of EGF receptor 2 (ERBB2, HER2) has been demonstrated in primary lung mucinous adenocarcinomas, which were characterized by KRAS activating mutations as well as very high levels of MUC5AC production." (PMID 22676183, 2012). "Similarly, KRAS mutations, which are common in intestinal‐type mucinous adenocarcinomas, may serve as a molecular marker to distinguish them from the usual types." (PMID 40317696, 2025). "Notably, mucinous adenocarcinoma with intrapulmonary metastasis harboring concurrent KRAS and GNAS mutations was identified in a 14-year-old boy with type 1 CPAM, suggesting that GNAS mutations may play a critical role in tumor progression and metastasis." (PMID 40296044, 2025). "Similar to low grade serous carcinomas, mucinous carcinoma and adjacent MBT and mucinous cystadenoma show the same KRAS mutation, supporting the hypothesis of the “adenoma-carcinoma sequence” and the view that mucinous carcinomas develop in a stepwise fashion from mucinous cystadenomas and MBTs." (PMID 24868556, 2014). "Mucinous adenocarcinoma was more common in tumors with BRAF/NRAS mutations (two of six cases, 33.3%) compared with KRAS-mutated tumors (six of 39 cases, 15.4%) or WT tumors (two of 27 cases, 7.4%)." (PMID 41439081, 2025). "In a patient-derived xenograft model, HMucBOT-1 retained MBOT morphology, whereas HMucBOT-2 exhibited features of mucinous carcinoma with undifferentiated components, with unique genetic alterations, including KRAS amplification." (PMID 40427213, 2025).
mucinous adenocarcinoma (continued). "In conclusion, a subset of HNF4α-positive adenocarcinomas, such as mucinous adenocarcinomas with gastrointestinal differentiation, are TTF-1-negative and SMARCA4 retained, often showing KRAS mutations." (PMID 38710944, 2025). "Molecular analysis of these mucinous cells has revealed various mutations, including KRAS, EGFR, and others, which are similar to those commonly found in de novo mucinous adenocarcinomas in adults." (PMID 39229431, 2024). "Among adenocarcinomas, the proportion of mucinous adenocarcinomas tended to be more frequent among KRAS‐positive patients." (PMID 37751775, 2023). "On the contrary, no morphologic patterns were described to be associated with KRAS and BRAF mutations except for mucinous adenocarcinomas, which were associated with a higher probability of BRAF mutation." (PMID 38201408, 2023). "KRAS‐positive patients were more likely to have mucinous adenocarcinoma compared to KRAS‐negative patients in the blood sample–positive and tissue sample–positive groups, respectively." (PMID 37751775, 2023). "Low BMI, histology of non-mucinous adenocarcinoma (ADC), LVI, PNI, and KRAS mutation were all independent risk factors for poor DFS." (PMID 35905109, 2022). "Here, we present a case of pulmonary invasive mucinous adenocarcinoma diagnosed based on KRAS G12D detection using this novel panel." (PMID 35545933, 2022). "Mucinous carcinomas are uncommon tumors associated with copy-number loss of CDKN2A and KRAS alterations and metastasis from other sites should always be considered in the differential diagnosis." (PMID 33919741, 2021). "Consistent with this dichotomy, molecular data confirm a distinct mutational profile of intestinal type and related colloid carcinomas, characterized mainly by the higher prevalence of GNAS mutations and lower rate of KRAS alterations." (PMID 34201897, 2021). "Liu and colleagues reported KRAS and GNAS are the most commonly mutated genes in LAMNs and low-grade mucinous adenocarcinomas with PMP." (PMID 33712927, 2021). "Among the 10 colloid adenocarcinoma subtype (COL) patients, 30% (3/10) were positive for KRAS mutations." (PMID 31692283, 2020). "Type I EOCs including low grade serous and mucinous carcinomas are typically Kirsten rat sarcoma viral oncogene homolog (KRAS)- and v-Raf murine sarcoma viral oncogene homolog B (BRAF)-mutated." (PMID 32605254, 2020). "NRG1 rearrangements accounted for a large portion of Invasive Mucinous Adenocarcinoma (IMA) of the lung of Asian patients, both in KRAS-wild type and KRAS mutated tumors." (PMID 29515761, 2018). "Herein, we present a unique case of pulmonary minimally invasive mucinous adenocarcinoma harboring a KRAS mutation in a 9-year-old girl without CPAM and provide a literature review of its clinical, radiographic, and histopathological features." (PMID 40296044, 2025). "The results obtained herein revealed the absence of common driver mutations other than KRAS mutations in mucinous adenocarcinomas (60%, 9/15 cases)." (PMID 38710944, 2025). "The distribution of KRAS mutations did not significantly differ between adenocarcinoma and mucinous adenocarcinoma (p-value = 0.545)." (PMID 38465160, 2024).
mucinous adenocarcinoma (continued). "Among mucinous tumors, KRAS mutations are almost exclusively found in invasive mucinous adenocarcinomas (69%), with no KRAS mutations detected in adenocarcinoma in situ and colloid carcinoma." (PMID 38953007, 2024). "KRAS is a genetic profile of invasive mucinous adenocarcinoma of the lung." (PMID 39507527, 2024). "The KRAS mutation positivity rate by tissue was 35.7% in patients with mucinous adenocarcinoma and 50.0% in patients with nonmucinous adenocarcinoma (data not shown)." (PMID 37751775, 2023). "In contrast, another study found an association between mucinous adenocarcinoma and KRAS mutations, but not with NRAS or BRAF mutations." (PMID 35681771, 2022). "The one without concurrent KRAS mutation had a histological appearance of colloid carcinoma, with somatic ATM and APC mutation." (PMID 35180847, 2022). "Another study found an association between mucinous adenocarcinoma and KRAS mutations, but not with NRAS or BRAF mutations." (PMID 35681771, 2022). "We found that the incidence of mutations in the KRAS gene was related to gender, depth of invasion, and TNM stage in CRC, but not related to age, lymph node metastasis, tumor location, tumor differentiation, or mucous adenocarcinoma." (PMID 33995628, 2021). "Invasive mucinous adenocarcinoma (mucinous bronchioloalveolar carcinoma) has been known to correlate with KRAS mutation and harbor no EGFR mutation." (PMID 26318038, 2015). "Major rationales for changes in adenocarcinoma histologic variants are that the invasive mucinous type shows frequent mutations in KRAS and hardly any in EGFR, whereas non-mucinous adenocarcinoma of predominant lepidic subtype is characterized by frequent mutations in EGFR and fewer in KRAS." (PMID 24879454, 2014). "Sites of metastasis and KRAS mutation positivity rate in nonmucinous and mucinous adenocarcinoma." (PMID 37751775, 2023). "In addition, the KRAS mutation detection frequencies were 35.7% in patients with mucinous adenocarcinoma and 50.0% in patients with nonmucinous adenocarcinoma (data not shown)." (PMID 37751775, 2023). "Notably, Davison and colleagues have reported that, in their series, none of the high-grade mucinous adenocarcinomas with a predominant signet ring cell component had KRAS mutation." (PMID 33712927, 2021). "Furthermore, an in vivo study showed that cetuximab, an epithelial growth factor receptor inhibitor, is effective for the treatment of mucinous carcinomas without KRAS mutations." (PMID 34885229, 2021). "For instance, a t-SNE cluster enriched for KRAS-mutant cases exhibited high expression of both HNF4A and MUC5AC, which are expressed at high levels in invasive mucinous adenocarcinoma, a distinct histological subtype of LADC18." (PMID 41198678, 2025). "Our data for both KRAS and BRAF were similar to previously reported rates in mucinous adenocarcinoma, and further stratification indicates similar characteristics of AWMC and AC in each specific location." (PMID 32582557, 2020). "All cases of mucinous, enteric, and colloid adenocarcinoma were HNF4α-positive, TTF-1-negative, and SMARCA4 retained, and showed a high frequency of KRAS mutations (10/18, 55.6%) and no EGFR mutations (0/18, 0%)." (PMID 38710944, 2025). "NRG1 gene fusion, which has been reported in KRAS wild-type mucinous adenocarcinomas, was not examined in the present study." (PMID 38710944, 2025).
mucinous adenocarcinoma (continued). "In KRAS‐positive patients with lung metastasis only, only one nonmucinous adenocarcinoma had a positive blood sample, and the others all had mucinous adenocarcinomas with positive tissue samples only." (PMID 37751775, 2023). "Of the 27 liquid KRAS‐positive patients with adenocarcinoma, 25 were diagnosed histologically, seven (28.0%) had mucinous adenocarcinoma and 18 (72.0%) had nonmucinous adenocarcinoma." (PMID 37751775, 2023). "We reported liquid KRAS‐positive NSCLC was different from KRAS‐positive tested by NGS with tissue samples (tissue KRAS‐positive) between mucinous adenocarcinoma and nonmucinous adenocarcinoma." (PMID 37751775, 2023). "The percentage of KRAS positive cases by histology based on liquid samples was 22.6% (7 of 31) in patients with mucinous adenocarcinoma and 58.1% (18 of 31) in patients with nonmucinous adenocarcinoma." (PMID 37751775, 2023). "Significantly higher KRAS MAF levels were detected in patients with G2 tumor grading, liver metastasis, and in those who did not undergo surgery at site of primary tumor; as for NRAS, significantly higher levels were found in patients with mucinous adenocarcinoma or with lung metastasis." (PMID 37296579, 2023). "Similarly, Liao and colleagues recently showed that HAMN and LAMN share high rates of KRAS and GNAS co-mutations supporting a common histogenesis and distinguishing them from mucinous adenocarcinoma, which is characterized by KRAS mutations in the absence of GNAS alterations." (PMID 33712927, 2021).
endometriosis (89 papers, 2008 to 2025). The growth of functional endometrial tissue in anatomic sites outside the uterine body. "Mutations in KRAS stimulate pathways that increase cell survival and proliferation and are associated with progesterone resistance in adenomyosis and endometriosis." (PMID 39903727, 2025). "Although other studies did not make this direct comparison, their data were also suggestive that the eutopic endometrium of endometriosis patients contained a higher frequency of KRAS mutations compared with those of endometriosis-free patients." (PMID 40590223, 2025). "Endometriosis demonstrates a significant genetic basis, with mutations in specific genes, including KRAS, PTEN, and ARID1A, actively being researched to comprehend their association with the increased risk of developing DE." (PMID 39859551, 2025). "KRAS mutations, the most common somatic mutations currently reported in endometriosis, ranging from 19.4 to 46.7%, result in increased cell proliferation and differentiation through enhanced GDP/GTP exchange and reduced GTPase activity." (PMID 39859551, 2025). "Despite biophysiological effects of KRAS mutation on endometriotic cell are reported, little is known about clinical features and clinical progesterone response of KRAS-mutated endometriosis." (PMID 38666954, 2024). "At the same time, the most common genetic alterations in endometriosis-associated CCC affect the KRAS/PI3K pathway." (PMID 39768828, 2024). "Endometriosis itself is a benign disease; however, it has been reported that endometriosis has KRAS, PIK3CA, or other cancer-associated mutations." (PMID 38666954, 2024). "Although endometriosis is a benign disease, it is associated with cancer-related gene mutations, such as KRAS or PIK3CA." (PMID 38666954, 2024). "KRAS somatic‐cancer driver mutations were associated with greater anatomic disease burden in endometriosis and thus more surgical complexity." (PMID 36977195, 2023). "Somatic activating KRAS mutations appear to be the most common somatic mutations currently reported in endometriosis, ranging from 19.4 to 46.7% of cases based on previous literature." (PMID 36977195, 2023). "There are indications of KRAS mutation as a key factor in a shared pathophysiology of endometriosis and adenomyosis." (PMID 38254632, 2023). "From the 122 subjects, a total of 262 endometriosis lesions were sampled for the KRAS mutation assay based on our selective sampling strategy: 105 DIE samples, 44 OMA samples, and 113 SUP samples." (PMID 36977195, 2023). "Somatic activating KRAS codon 12 mutations were detected in endometriosis lesions using droplet digital PCR." (PMID 36977195, 2023). "Recently, our genomic analysis of endometriosis and normal endometrium revealed the presence of somatic mutations in cancer-associated genes such as KRAS and PIK3CA in endometriotic and normal endometrial epithelial cells." (PMID 38067342, 2023). "In conclusion, KRAS mutations were associated with greater anatomic severity of endometriosis, resulting in increased surgical difficulty." (PMID 36977195, 2023). "They found that KRAS mutations are more frequent in cases of adenomyosis with co-occurring endometriosis, low progesterone receptor expression, or dienogest pretreatment." (PMID 37834773, 2023). "Perhaps the most significant development is the finding of common mutations, particularly of KRAS, in adenomyosis and endometriosis." (PMID 38254632, 2023). "In this study, we describe a prospective longitudinal cohort of patients undergoing surgery for endometriosis, with somatic activating KRAS codon 12 mutation testing in excised endometriosis lesions after pathology review and tissue enrichment." (PMID 36977195, 2023). "The objective of the study was to characterize the clinical phenotype of KRAS mutations in endometriosis." (PMID 36977195, 2023).